Y_RNA (Y RNA )
Gene: Miscellaneous RNA gene on chromosome 6 (106,420,706 to 106,420,807, forward strand). Ensembl gene ENSG00000207499.
Homologues: Orthologues: macaque Y_RNA (95% identical), guinea pig Y_RNA (92% identical). Paralogues in human: RNY3 (93% identical), Y_RNA (93% identical), RNY3P1 (92% identical), Y_RNA (92% identical), Y_RNA (91% identical), RNY3P16 (90% identical), Y_RNA (90% identical), Y_RNA (89% identical), RNY3P14 (88% identical), Y_RNA (88% identical), RNY3P11 (87% identical), RNY3P5 (87% identical), and 98 more.